SUV39H1 (SUV39H1 histone lysine methyltransferase)
Diseases named in the same sentence as SUV39H1 in open-access papers (continued):
Sharing a sentence is not in itself a finding about the gene and the disease.
tumor (continued). "A recent study showed that silencing of SUV39H1 markedly inhibited ccRCC cell proliferation and tumor growth in vivo and in vitro via inducing G2/M phase cell cycle arrest." (PMID 34922551, 2021). "SUV39H1 has been reported to facilitate tumor progression by inhibiting the expression of retinoblastoma." (PMID 34922551, 2021). "For the purpose of investigating SUV39H1 mediated the costimulatory factors Tim-3 and galectin-9 expression through DNA methylation in vivo, we generated SiHa-SUV39H1 and HeLa-SUV39H1 tumor xenografts in nude mice." (PMID 32699524, 2020). "Our studies revealed a tumor suppressive role of Suv39h1 in MLL-r AML that is partially mediated by inactivation of Hoxb13 and Six1, as well as reversion of Hoxa9/Meis1 downstream transcriptomes." (PMID 33037410, 2020). "Given the importance of PRC2 as a histone methyltransferase in HCC, we further investigated the interaction between CRNDE and EZH2, SUZ12, and SUV39H1, and found that the inhibitory effect of EZH2, SUZ12, and SUV39H1 on tumor suppressors was mediated by CRNDE." (PMID 32826865, 2020). "Collectively, these results suggest a tumor suppressive role of SUV39H1 in both MLL-r AML mouse model and human cell line." (PMID 33037410, 2020). "The tumor-suppressive role of SUV39H1 has been shown before in a mouse model of retinoblastoma and this tumor-suppressive role is recapitulated in zebrafish, supporting its importance and evolutionary conservation." (PMID 31731811, 2019). "A genetic screen done in zebrafish identified the histone H3 lysine 9 histone methyltransferase, SUV39H1, out of other chromatin-modifying factors, as a tumor suppressor." (PMID 31731811, 2019). "Then, we identified that the amplification percentages of SUV39H2 in different tumor stages were consistently higher than those of SUV39H1." (PMID 30348215, 2018). "It was proposed that TGFβ drives Myc-induced senescence in a Suv39h1-dependent manner raising the intriguing possibility that BCOR also regulates this unique tumour suppressive mechanism." (PMID 28262675, 2017). "Of these factors, SUV39H1 emerged as the strongest modifier, significantly suppressing tumor formation from 12 dpf by the logrank test (p = 0.0001)." (PMID 23705022, 2013). "SUV39H1-overexpressing tumors had a delay in tumor onset, so the Kaplan-Meier curve appears suppressed from the beginning of the assay at 12 dpf." (PMID 23705022, 2013). "The identification of SUV39H1 as a suppressor of RMS onset in our zebrafish model supports these studies and the notion that SUV39H1 functions as a tumor suppressor." (PMID 23705022, 2013). "We identified specific H3K4 and H3K9 methyltransferases, such as Mll, Mll3, Setd1a, Ehmt2, Suv39h1, and Setdb1 as biomarkers of residual tumor cells persisting after chemotherapy." (PMID 23520493, 2013). "The involvement of HNRPD and SUV39H1 is further supported by reports that the tumor suppressor miR-125 is downregulated in both NSCLC and SCLC." (PMID 24564251, 2013). "Previous studies involving SUV39H1 have demonstrated its role as a tumor suppressor involving cell cycle regulation." (PMID 23705022, 2013). "Our data indicate that SUV39H1 overexpression affects the initiation of tumors, but once the tumor initiates, it grows at the same rate as control tumors." (PMID 23705022, 2013). "SUV39H1-overexpressing and control tumors have a similar proliferation rate, muscle differentiation state, and tumor growth rate." (PMID 23705022, 2013). "With SUV39H1 as a potential tumor suppressor in RMS, we looked to the Oncomine database to evaluate the status of SUV39H1 expression in human RMS." (PMID 23705022, 2013). "The critical roles for Suv39h1/2 and H3K9me3-mediated chromatin remodeling in aging are highlighted by the findings that loss of Suv39h1 ablates OIS in tumor mouse model, while Suv39h1 overexpression leads to growth retardation." (PMID 23633913, 2012).
tumor (continued). "An H3K9 histone methyltransferase, Suv39H1, has been shown to function as a tumor suppressor by maintaining H3K9 methylation levels." (PMID 21445275, 2011). "In a patient-derived xenograft model, targeting SUV39H1 inhibits GSC-driven tumor growth." (PMID 40059829, 2025). "The effects of SUV39H1 knockout on T cell effector functions have demonstrated variability across studies, likely due to differences in disease models (tumor vs. virus), T cell activation methods (TCR vs. CAR), and therapeutic approaches (PD-1 blockade vs. T cell therapy)." (PMID 40093905, 2025). "Suv39H1 mRNA expression was lower in normal adjacent tissues than in LUAD tumor tissues." (PMID 38424632, 2024). "SUV39H1 may be a tumor suppressor, involved in the occurrence and development of various types of tumors by promoting cell senescence and inhibiting genes required for cell proliferation." (PMID 38650654, 2024). "In OSCC, the expression of SUV39H1 is significantly increased, which is significantly related to tumor size, suggesting that SUV39H1 may play a role in promoting tumor development in OSCC." (PMID 38650654, 2024). "In summary, as a SUV39H1-specific inhibitor, chaetocin may suppress tumor growth and increase the sensitivity of BC cells to cisplatin by up-regulating PPP2R2B expression." (PMID 38976080, 2024). "Previous studies have suggested that SUV39H1 plays a role in tumor inhibition." (PMID 38017386, 2023). "These two latter experiments suggest that the increased tumor control observed in Suv39h1-defective mice could be attributed, at least partially, to an increased anti-tumor activity of Suv39h1-KO CD8+ T cells." (PMID 35768432, 2022). "Therefore, the absence of Suv39h1 expression not only leads to higher CD8+ T-cell tumor-infiltration upon anti-PD-1 treatment, but also a change in the phenotype of the infiltrating cells, away from memory and towards a more pronounced effector phenotype." (PMID 35768432, 2022). "Furthermore, H1299 cells expressing wild-type SUV39H1 proliferated slower than those expressing SUV39H1-2KR with mutated methylation loci, suggesting that genome instability induced by SUV39H1 methylation restrains cell proliferation and tumor growth." (PMID 35069908, 2022). "These defects in constitutive heterochromatin are most evident in SUV39H1 and SUV39H2 double knockout mice, which exhibit reduced embryonic viability, small stature, chromosome instability, an increased risk of tumor formation and male infertility owing to defective spermatogenesis." (PMID 34357075, 2021). "This evidence indicated the possibility that in NSCLC, upregulated SUV39H1 may contribute to tumor progression by regulating BMP4." (PMID 33472665, 2021). "Thus, our study has connected the gap between downregulated miR-744 in tumor cell-derived EVs and upregulated SUV39H1 promoted NSCLC development." (PMID 33472665, 2021). "Mechanistically, a large number of biomolecules and tumor-associated signaling pathways, including DECR1, PANX2, HSPB1, ACOT8, SUV39H1, NCOA4, PI3K-AKT-mTOR signaling, VHL/HIF-2α pathway, and Hippo/TAZ signaling pathway, have been reported to regulate ferroptosis in urologic cancers." (PMID 34922551, 2021). "Furthermore, SUV39H1 inhibitor F5446 synergized with anti-PD-1 immunotherapy to prevent tumor growth and increase mouse survival." (PMID 33681705, 2021). "Thus, there is sufficient evidence to show that SUV39H1 is involved in regulating tumor growth, metastasis, and cell proliferation." (PMID 34066975, 2021). "Our data revealed that SUV39H1 functions as a tumor suppressor in MLL-AF9-induced AML progression." (PMID 33037410, 2020). "Our data thus strongly indicated Suv39h1 as a tumor suppressor for MA9 AML." (PMID 33037410, 2020). "Conversely, SUV39H1 regulates cell migration and tumor growth." (PMID 31013771, 2019).
tumor (continued). "SUV39H1 inhibition with chaetocin or RNAi-mediated SUV39H1 knockdown led to reduced tri-methylation of lysine 9 in histone 3 (H3K9me3), re-expression of silenced tumor suppressor genes and apoptosis induction in vitro and reduced tumor growth in vivo." (PMID 27863389, 2016). "Our studies provide evidence for the role of SUV39H1 as a tumor suppressor." (PMID 23705022, 2013). "SUV39H1 overexpression may silence cyclin B1, leading to growth arrest and decreased tumor initiation." (PMID 23705022, 2013). "Therefore, future research should investigate the pathways that SUV39H1 regulates in its role as a tumor suppressor, with particular focus on cell cycle regulation." (PMID 23705022, 2013). "CREBBP and SUV39H1 upregulation was observed in breast cell lines compared tobreast tumours." (PMID 16638127, 2006). "SUV39H1 may also play a carcinogenic role in some tumor types." (PMID 38650654, 2024). "However, SUV39H1 has also been reported as a tumor promoter in recent years." (PMID 38017386, 2023). "Mice that received Suv39h1-KO OT-1 T cells controlled tumor growth better than mice that received littermate WT OT-1 T cells, demonstrating that Suv39h1 deficiency in CD8+ T cells augments their anti-tumor potential in the absence of any other Suv39h1-defective cell type." (PMID 35768432, 2022). "Dysregulation of JMJD2 thus may counteract the tumor suppressive function of Suv39H1." (PMID 21445275, 2011). "For example, CRISPR-Cas9 inactivation of the H3K9 trimethyltransferase SUV39H1 in CAR-T cells promoted a self-renewing and stem-like phenotype that allowed for the long-term persistence of CAR-T cells and protection against tumor relapse." (PMID 41181132, 2025). "Targeting SUV39H1 leads to reduced GSC maintenance, increased sensitivity to TMZ chemotherapy, and impaired GBM tumor growth in mice." (PMID 40059829, 2025). "SUV39H1 inhibition results in DPP4 upregulation and ferroptosis induction, suggestive of tumor suppressive DPP4 role." (PMID 37563650, 2023). "We conclude that, similar to the Suv39h1-genetic defect, treatment of WT tumor-bearing mice with the Suv39h1 inhibitor ETP-69 reduces tumor growth, especially in combination with anti-PD-1." (PMID 35768432, 2022). "Next, we investigated the impact of CRNDE on several tumor suppressor genes that are reported to be inhibited by EZH2, SUZ12, and SUV39H1-mediated histone trimethylation." (PMID 32826865, 2020). "SUV39H1 overexpression significantly up-regulated the methylation level of HAVCR2 and LGALS9 in tumor tissues." (PMID 32699524, 2020). "ChIP analysis revealed that SUV39H1 regulated the expression of DNMT3A by improving H3K9me3 level acting on the − 1000 to + 1 region of the promoter region of DNMT3A in tumor tissues." (PMID 32699524, 2020). "Factors, for example, tumour suppresser gene, KLLN, can also regulate H3K9me3 by altering SUV39H1 activity through interaction with DBC127." (PMID 28779172, 2017). "Several novel genes also positively correlated with TN disease, high Ki67 levels and tumor grade: DNMT3B, SUV39H1 and SUV39H2." (PMID 27863398, 2016). "SUV39H1 was determined to be a suppressor of RMS formation, dependent on its histone methyltransferase activity, suppressing tumor initiation likely regulation of the cell cycle." (PMID 23705022, 2013). "Thus, SUV39H1‐disrupted CAR‐T cells have an improved stemness/memory and reduced effector/exhausted phenotype, thereby exerting more potent tumor rejection and more persistent protection in both lung adenocarcinoma and B‐ALL models." (PMID 38645666, 2024).
tumor (continued). "In the tumor tissue derived from A549 and H2199 NSCLC cells, protein levels of RUNX3 were increased when MEX3C was inhibited but Suv39H1 protein levels were lower, indicating that RUNX3 could negatively control Suv39H1." (PMID 38424632, 2024). "Moreover, pharmacological inhibition of KMT1A (also known as SUV39H1) with chaetocin increased apoptosis of HCC cells in vitro and in xenograft subcutaneous tumours." (PMID 36650321, 2023). "More importantly, SUV39H1 has a non-negligible role in the dysfunction of tumor-infiltrating cells (CTL)." (PMID 36713412, 2022). "Bioinformatics analysis revealed that the expressions of HOTAIR and Suv39H1 were higher in tumor tissues than those in noncancerous tissues." (PMID 35619625, 2022). "Tumor bearing littermate WT and Suv39h1-KO mice were randomly assigned to two groups, treated or not with anti-PD-1 monoclonal Ab after establishment of the tumors." (PMID 35768432, 2022). "While the SUV39H1-overexpressing mature tumors do not display differences in tumor proliferation and muscle differentiation status, our studies establish that larval fish with ectopic SUV39H1 expression initiate fewer tumors." (PMID 23705022, 2013). "As far as we know, however whether SUV39H1 is related to tumor angiogenesis has not been reported in the literature." (PMID 38650654, 2024). "In addition to the 8 representative PKMTs with tumor suppressor activity, PRDM16, MLL2, MLL4, SET domain bifurcated histone lysine methyltransferase 1 (SETDB1), SETD3, NSD1, NSD3, DOT1L, SUV39H1, and SUV39H2 have also been suggested to possess tumor suppressor activity." (PMID 38036730, 2023). "Moreover, our data indicate that in the absence of Suv39h1, CD8+ TILs are poised to more effectively respond to TCR-activation and to become highly cytolytic upon PD-1-blockade, underlying the increased tumor rejection compared to WT mice." (PMID 35768432, 2022). "However, the Suv39h1-defective TILs also express a strong IFN-I signature, and respond vigorously to PD-1 blockade, inducing potent tumor rejection and showing broader chromatin accessibility, in particular around genes linked to effector functions, as compared to wild type cells." (PMID 35768432, 2022). "Because CyclinD1 inhibited Dicer expression by chromatin modifications, we further performed ChIP assays to determine whether altered CyclinD1 expression could also modulate the HP1α, H3K9me3 and SUV39H1 expression in the SOX2 and HOXA2 promoters in ICC and non-tumor HIBEpic cells." (PMID 31590696, 2019). "We further showed that both metformin treatment and SUV39H1 knockout in PCa cells can reduce integrin αV and β1 proteins, as well as their downstream phosphorylated focal adhesion kinase (FAK) levels, which is essential for functional adhesion signaling and tumor cell migration." (PMID 28459432, 2017). "It is worth noting that the correlation between SUV39H1 and NOTCH1 and MVD is weak, which may indicate that SUV39H1 may not be directly involved in tumor angiogenesis in OSCC." (PMID 38650654, 2024). "However, in the absence of this epigenetic barrier imposed by Suv39h1, TCR-mediated reactivation is restored, and leads to highly cytolytic effectors with anti-tumor potential." (PMID 35768432, 2022).
infection (7 papers, 2017 to 2025). The state of being infected such as from the introduction of a foreign agent such as serum, vaccine, antigenic substance or organism. "In addition, IFI16 is responsible for SUV39H1 recruitment to viral DNA during de novo infection and latency of Kaposi’s sarcoma-associated herpesvirus." (PMID 35350437, 2022). "To this end, we used both gain‐of‐function and loss‐of‐function approaches, and either overexpressed Suv39h1 by Ad‐Suv39h1 infection or knocked down the endogenous Suv39h1 by LV‐Suv39h1." (PMID 31736204, 2020). "Ad‐Suv39h1 local infection increased the expression of Suv39h1 by approximately 3 times (P < .05, as compared to Ad‐Null), while LV‐Suv39h1 reduced it by almost 40% in the injured vessels (P < .05, as compared to LV‐NC)." (PMID 31736204, 2020). "Functionally, we observed enhanced neointima formation following local infection with Ad‐Suv39h1." (PMID 31736204, 2020). "In addition, knocking down Suv39h1 by LV‐Suv39h1 infection led to a significant reduction of neointima formation, as measured by IA and the I/M ratio (both P < .05, as compared to LV‐NC)." (PMID 31736204, 2020). "Here, we show that IFI16 is in complex with the H3K9 methyltransferase SUV39H1 and GLP and recruits them to the KSHV genome during de novo infection and latency." (PMID 31682228, 2019). "Together, these results suggested that IFI16 is instrumental in recruiting H3K9MTase SUV39H1 and GLP onto KSHV lytic promoters during de novo infection, resulting in deposition of the heterochromatin H3K9me3 mark." (PMID 31682228, 2019). "Demonstration of IFI16’s specific interaction with GLP and SUV39H1 and the effect of IFI16 KD upon the recruitment of SUV39H1 and GLP to the KSHV genome during de novo infection." (PMID 31682228, 2019). "In the si-SUV39H1+si-SPP1 group, 1 rat died from infection and 1 from heart failure." (PMID 36193085, 2022). "Suv39h1 expression level was markedly elevated in VSMCs after Ad‐Suv39h1 infection for 3 days, but not in VSMCs infected with Ad‐Null." (PMID 31736204, 2020). "When we re-expressed full-length SUV39H1 or SUV39H1ΔSET in the KO cells via stable infection of retrovirus, the cell migration was rescued by re-expression of SUV39H1 but not by re-expression of SUV39H1ΔSET in the KO cells." (PMID 28459432, 2017).
adenocarcinoma (3 papers, 2013 to 2023). A common cancer characterized by the presence of malignant glandular cells. "Additionally, loss of SUV39H1 in Rb heterozygote mice leads to the development of C cell adenocarcinomas, along with frequent expression of proliferation markers, suggesting that SUV39H1 suppresses tumors through senescence." (PMID 23705022, 2013).
cardiac disease (2 papers, 2023). "Studies in mice and cell lines similarly, yet indirectly, suggest a role for SUV39H1 in cardiac disease." (PMID 37504561, 2023).
bacterial infections (1 paper, 2021). "Furthermore, SUV39H1 has been connected to immune function and bacterial infections, because the mycobacterial histone-like HupB protein has been shown to be methylated by SUV39H1 and this process participates in host defense." (PMID 34357075, 2021).
SUV39H1 also shares sentences with these, for which no sentence is quoted: non-small cell lung carcinoma (2 papers); adenoid cystic carcinoma (1); allergic asthma (1); amnesia (1); asthma (1); autism (1); bladder urothelial carcinoma (1); cervical squamous cell carcinoma (1); dementia (1); diabetic retinopathy (1); diffuse astrocytoma (1); diffuse intrinsic pontine glioma (1); endothelial dysfunction (1); esophageal squamous cell carcinoma (1); gastric tumors (1); graft versus host disease (1); hematological malignancies (1); high-grade gliomas (1); liposarcoma (1); lung squamous cell carcinoma (1); myeloma (1); ovarian cancer (1); pilocytic astrocytoma (1); salivary gland tumors (1); stomach adenocarcinoma (1).